CREB3L1 (cAMP responsive element binding protein 3 like 1)
Diseases named in the same sentence as CREB3L1 in open-access papers (continued):
Sharing a sentence is not in itself a finding about the gene and the disease.
prostate carcinoma (4 papers, 2018 to 2024). A carcinoma that arises from epithelial cells of the prostate gland. "The expression of CREB3L1 in prostatic cancer cell line LNCaP is moderate, knocking down CREB3L1 attenuates p21 expression." (PMID 38164349, 2024). "And bioinformatics analysis using RegNet Driver revealed CREB3L1 as a novel transcription factor functioned in prostatic cancer." (PMID 38164349, 2024). "In prostate cancers, there are frequent structural rearrangements in the regulatory regions of the CREB3L1 gene, that are predicted to contribute to tumorigenesis." (PMID 35802566, 2022). "Similar to F3 and CREB3L1, the upregulation of ORM1 (by 174.684-fold) indicated that the progression of prostate cancer in LNCaP xenograft tumor might be driven by an inflammatory tumor microenvironment." (PMID 33808801, 2021).
virus infection (4 papers, 2016 to 2023). "The gene with the second highest expression, CREB3L1, has been reported to be regulated by intramembrane proteolysis in response to virus infection." (PMID 33808801, 2021). "Viral infections and treatment with the chemotherapy agent, doxorubicin, have also been shown to induce cell stress and the activation of CREB3L1." (PMID 26810754, 2016). "CREB3L1 is activated in response to increased cAMP levels and is involved in stress response, regulation of cell secretory capacity, extracellular matrix production, cell migration, and virus infection response." (PMID 37784136, 2023). "DEGs involving in virus infection were observed in the PPI network including CREB3L1, FDPS and IRS2, in which CREB3L1 was reported to be associated with iCell hepatocyte (induced pluripotent stem cell derived hepatocytes from Cellular Dynamics International) susceptibility to HBV infection." (PMID 26900848, 2016).
renal cell carcinoma (3 papers, 2015 to 2022). "In the current study, we used a mouse xenograft model of renal cell carcinoma (RCC), which exhibits the same drug sensitivity as that displayed in patients, to demonstrate that doxorubicin inhibited growth of tumors that produced CREB3L1 but not those that did not express the protein." (PMID 26110425, 2015).
skin cutaneous melanoma (3 papers, 2016 to 2025). "However, higher levels of CREB3L1 expression in skin cutaneous melanoma have been positively correlated with poorer overall survival, suggesting that, in melanoma, CREB3L1 promotes tumor growth and development." (PMID 40699755, 2025).
uterine corpus endometrial carcinoma (3 papers, 2016 to 2022). A endometrial carcinoma (disease) that involves the body of uterus. "In patients with SKCM, uterine corpus endometrial carcinoma (UCEC), esophageal adenocarcinoma (ESCA), CHOL, and head and neck squamous cell carcinoma (HNSC), the high CREB3L1 gene alteration rate was occurred, in which the alteration frequency was higher than 2%." (PMID 36171879, 2022).
brain glioma (2 papers, 2018 to 2024). A malignant glioma that involves the brain. "Except for the cultivated astrocytes, CREB3L1 expression in brain glioma tissues was also recorded." (PMID 38164349, 2024). "The purpose of the present study was to explore clinical roles of CREB3L1 and PTN expression in brain glioma progression." (PMID 29531016, 2018). "Our results indicate that the CREB3L1 and PTN expression are useful indicators that help to identify the nature of the glial cells and malignant degrees of brain gliomas." (PMID 29531016, 2018). "In conclusion, the present study indicates that the CREB3L1 and PTN expressions provide a clinical cue in helping to realize grade of brain glioma cells." (PMID 29531016, 2018). "The present study was conducted to investigate the clinical significance of cAMP responsive element binding protein 3 like 1 (CREB3L1) and pleiotrophin (PTN) expression in prognosis of patients with brain gliomas." (PMID 29531016, 2018). "In contrast with the CREB3L1-positive patients, a decrease in survival proportion (%) for the CREB3L1-negative patients was more obvious with an initial decrement observed at the time point of the seventh month after the brain glioma was surgically excised." (PMID 29531016, 2018). "Our study could provide an important clue to the clinical roles of CREB3L1 and PTN expressions in evaluating grade-versions of brain gliomas, and thus may offer an appropriately therapeutic option for the cancer patients." (PMID 29531016, 2018). "Interestingly, in brain glioma the expression of CREB3L1 negatively correlates with PTN levels, absence of CREB3L1 accompanied by the presence of PTN implied a short survival time and poor prognosis for brain glioma patients." (PMID 38164349, 2024).
cholangiocarcinoma (2 papers, 2016 to 2022). A carcinoma that arises from the intrahepatic biliary tree (intrahepatic cholangiocarcinoma) or from the junction, or adjacent to the junction, of the right and left hepatic ducts (hilar cholangiocarcinoma). "CREB3L1, which is upregulated in S100P + SPP1− intrahepatic cholangiocarcinoma tumor cells, can facilitate the invasion of S100P + SPP1− perihilar large duct type tumor cells by directly targeting S100P." (PMID 36171879, 2022).
Insulin resistance (2 papers, 2020 to 2024). Increased resistance towards insulin, that is, diminished effectiveness of insulin in reducing blood glucose levels. "Venn diagram analysis revealed that seven DEGs (CXCL8, MLXIPL, CREB3L1, EGR1, NOTCH3, ACTA2, and SERPINE1) were associated with both obesity and diabetes-associated pathways, including non-alcoholic fatty liver disease, insulin resistance, thermogenesis, and apelin signaling pathways." (PMID 38570815, 2024).
liver cirrhosis (2 papers, 2023 to 2025). "In conclusion, BMSCs alleviate liver cirrhosis by modulating the Creb3l1/lncRNA Kcnq1ot1/miR‐374‐3p/Fstl1 signaling pathway." (PMID 37282819, 2023). "In summary, BMSCs alleviate liver cirrhosis by modulating the Creb3l1/lncRNA Kcnq1ot1/miR‐374‐3p/Fstl1 pathway." (PMID 37282819, 2023). "BMSCs alleviate liver cirrhosis by modulating the Creb3l1/lncRNA Kcnq1ot1/miR–374–3p/Fstl1 signaling pathway." (PMID 37282819, 2023). "BMSCs treatment also decreased the expression of Creb3l1 in mice with liver cirrhosis." (PMID 37282819, 2023).
Oligodontia (2 papers, 2020 to 2021). The absence of six or more teeth from the normal series by a failure to develop. "Except for the rare pathogenic variants in COL1A1, COL1A2, and CREB3L1, we were unable to identify any other pathogenic variant in a shared gene in the cohort that could explain the phenotype of oligodontia." (PMID 32234057, 2020). "Our findings suggest that mutations in COL1A1, COL1A2, and CREB3L1 may cause hypodontia and oligodontia in OI." (PMID 32234057, 2020). "Finally, we suggest CREB3L1 as a candidate gene to be included in the genetic investigation of individuals presenting with oligodontia." (PMID 32234057, 2020). "In that study, treatment with BPs was not considered; instead, the very high prevalence of hypodontia and oligodontia prompted the group to investigate whether mutations in genes other than those earlier associated with OI (COL1A1, COL1A2, and CREB3L1) were responsible for the disturbances." (PMID 33743023, 2021).
ovarian carcinoma (2 papers, 2021 to 2024). A malignant neoplasm originating from the surface ovarian epithelium. "We demonstrated that doxorubicin-mediated cell death in ovarian cancer cell lines was associated with nuclear translocation of CREB3L1 and that the effect was augmented by infection with oncolytic vaccinia virus or treatment with recombinant interferon (IFN)-β used as a viral surrogate." (PMID 34632049, 2021). "In this study, we investigated the effect of the oncolytic virus and doxorubicin used alone or in combination on activation of the cytoplasmic transcription factor CREB3L1 (cyclic AMP [cAMP] response element-binding protein 3-like 1) in ovarian cancer cell lines and clinical specimens." (PMID 34632049, 2021).
acute myeloid leukemia (1 paper, 2022). Acute myeloid leukemia (AML) is a group of neoplasms arising from precursor cells committed to the myeloid cell-line differentiation. "We found that CREB3L1 was expressed in 33 cancer types, in detail, CREB3L1 was expressed highest in PRAD while the lowest was in acute myeloid leukemia (LAML)." (PMID 36171879, 2022).
asthma (1 paper, 2023). "Furthermore, while the epigenetic effect of albuterol was independent of the asthma status, severity, and use of medication, BDR was nominally associated with the effect on the CpG cg23032799 (CREB3L1) (p = 0.004)." (PMID 37784136, 2023).
bipolar disorder (1 paper, 2025). A disorder of the brain that causes unusual shifts in mood, energy, activity levels and the ability to carry out day-to-day tasks. "Certain TFs such as ETS1, MAF, SMARCA2, TRPS1, and CREB3L1 appear to modulate TF-tagged genes in multiple traits, which could be key elements linking AD, bipolar disorder, and schizophrenia through shared regulatory pathways." (PMID 39905509, 2025).
bone metabolism disorders (1 paper, 2023). "Functional state changes of CREM, FOSL2, FOXC2, RUNX2, and CREB3L1 regulons regarding immunity, cell proliferation, and differentiation identified the important cell stages or subtypes that may be predominantly affected by bone metabolism disorders." (PMID 36793138, 2023).
brain ischemia (1 paper, 2022). Diminished or absent blood supply to the brain caused by obstruction (thrombosis or embolism) of an artery resulting in neurologic damage. "Upregulation of Creb3l1 was found proximal to the injury site, and Creb3l2 was also found in the peri-infarction region in a brain ischemia mouse model to restore the injury region." (PMID 35469040, 2022).
cognitive decline (1 paper, 2025). "Our investigations reveal that aging differentially modulates restraint stress-induced ER stress responses: while suppressing the upregulation of protective ER stress-related genes (Fmo2, Creb3l1, Tmtc3, Bak1), it promotes the induction of Pgap1 change associated with cognitive decline." (PMID 41200271, 2025).
diabetes (1 paper, 2024). "A whole-transcriptome study revealed differentially expressed target genes important in obesity and diabetes-related pathways such as MLXIPL, CREB3L1, EGR1, ACTA2, SERPINE1, NOTCH3, and CXCL8." (PMID 38570815, 2024).
diabetes insipidus (1 paper, 2022). A disorder characterized by excretion of large amounts of urine, accompanied by excessive thirst. "Animals with knockdown of Creb3l1 in the SON displayed classic signs of diabetes insipidus with increased fluid intake and the production of higher volumes of diluted urine (polyuria) compared to controls, likely due to insufficient release of AVP and OXT." (PMID 35803572, 2022).
diffuse large B-cell lymphoma (1 paper, 2015). "From patient tumor biopsies we analyzed, CREB3L1 was expressed in 19% of RCC, which is generally resistant to doxorubicin, but in 70% of diffuse large B-cell lymphoma that is sensitive to doxorubicin." (PMID 26110425, 2015).
fibrosarcoma (1 paper, 2019). A malignant mesenchymal fibroblastic neoplasm affecting the soft tissue and bone. "We found in our study that the expression of Creb3l1 was higher in the granulomas of Spalax compared to the fibrosarcomas and may have been an important factor in preventing the development of malignant fibrosarcoma." (PMID 30621584, 2019).
gastric cancer (1 paper, 2022). A primary or metastatic malignant neoplasm involving the stomach. "The results of our study indicated that ISL regulated the tumor microenvironment and inhibited GRP78 expression by downregulating the transcriptional factor CREB3L1 and suppressed stem cell–like characteristics in human gastric cancer cells." (PMID 35740372, 2022). "The inhibition of GRP78 expression in human gastric cancer cells by ISL is mediated by its transcriptional factor, CREB3L1." (PMID 35740372, 2022).
glaucoma (1 paper, 2026). Increased pressure in the eyeball due to obstruction of the outflow of aqueous humor. "Further mechanistic and in vivo studies will be required to determine whether modulation of CREB3L1-mediated pathways represents a viable therapeutic strategy in glaucoma." (PMID 41898280, 2026).
Gliosis (1 paper, 2022). Gliosis is the focal proliferation of glial cells in the central nervous system. "CREB3L1 (also named OASIS) was initially identified in a genetic in vitro screening performed in a model to study gliosis." (PMID 35455992, 2022).
intracranial aneurysm (1 paper, 2014). "Indeed, both CREB3L1 and MMP9 are up-regulated in intracranial aneurysm, which causes hemorrhage and is associated with MMP-mediated destabilization of the arterial wall." (PMID 25359725, 2014).
lung carcinoma (1 paper, 2023). "The CREB3L1 gene has been associated with lung cancer growth due to its involvement in the activation of alpha-smooth muscle actin (α-SMA)-positive cancer-associated fibroblasts (CAFs)." (PMID 37508851, 2023). "Therefore, studying the role of prolidase, CREB3L1, and COL1A1 gene expression in lung cancer appears to be significant." (PMID 37508851, 2023).
mammary adenocarcinoma (1 paper, 2022). "Our previous work demonstrated that CREB3L1 can function as a metastasis suppressor in the estrogen-dependent rat mammary adenocarcinoma cell line R3230AC." (PMID 35802566, 2022). "We previously characterized the role of CREB3L1 (cAMP responsive element binding protein 3 like 1) using derivatives of the estrogen-dependent rat mammary adenocarcinoma cell line R3230AC." (PMID 35802566, 2022).
osteoarthritis (1 paper, 2021). A noninflammatory degenerative joint disease occurring chiefly in older persons, characterized by degeneration of the articular cartilage, hypertrophy of bone at the margins and changes in the synovial membrane. "Creb3l1 is a transcription factor significantly upregulated at the early stage of osteoarthritis." (PMID 33407721, 2021).
ovarian tumor (1 paper, 2021). "This combination treatment was also effective in mediating nuclear translocation of CREB3L1 in cancer cells isolated from ovarian tumor biopsies at different stages of disease progression." (PMID 34632049, 2021). "To examine whether differences in CREB3L1 expression were associated with sensitivity of ovarian tumor cells to OVV and DOX treatment, we analyzed the treatment-induced nuclear translocation of CREB3L1 in specimens with different stages of tumor progression." (PMID 34632049, 2021).
prostate tumor (1 paper, 2017). "We report known prostate tumor regulatory drivers and nominate novel transcription factors (ERF, CREB3L1, and POU2F2), which are supported by functional validation." (PMID 28750683, 2017).
soft tissue tumors (1 paper, 2017). "CREB3L1 is a gene well known for its involvement in chimeric transcripts in soft tissue tumors." (PMID 28186972, 2017).
steatosis (1 paper, 2024). Increased lipid within the cytoplasm of cells. "A direct effect of CREB3L1 on steatosis formation is not described, but it hypothetically could be a result of collagen secretion by activated hepatic stellate cells, also since CREB3L1 has been linked to be essential for collagen secretion by other cell types." (PMID 39142818, 2024).
thyrotrope adenoma (1 paper, 2021). "Consistent with this, Creb3l1 is upregulated in a model of thyrotrope adenoma." (PMID 33858413, 2021).
uterine papillary serous carcinoma (1 paper, 2022). "In addition, the main type alteration was CREB3L1 missense mutation, while R309C alteration was detected in LUSC, R309H alteration was detected in uterine papillary serous carcinoma and R309L alteration was detected in KIRP." (PMID 36171879, 2022).
tumor (53 papers, 2012 to 2026). "TWIST1 and CREB3L1 are associated with tumor progression mediated by CAF-induced ECM remodeling and fibrosis." (PMID 40755770, 2025). "Our studies showed that loss of CREB3L1 in various models, including zebrafish and mouse xenografts, dramatically attenuated the invasiveness, metastasis, and tumor growth of ATC tumors." (PMID 36192735, 2022). "The associations between CREB3L1 expression and tumor mutation burden (TMB), and microsatellite instability (MSI) were assessed by spearman’s rank correlation coefficient." (PMID 36171879, 2022). "CREB3L1 levels increased with tumor stage, and patients with high CREB3L1 expression were at a greater risk of death." (PMID 36192735, 2022). "Loss of CREB3L1 inhibited metastasis and tumor growth of ATC xenografts in zebrafish and nude mouse model." (PMID 36192735, 2022). "The role of CREB3L1 in tumor phenotype is controversial: while some studies associated this TF with metastasis promotion, other studies suggest its role in metastasis inhibition." (PMID 33924679, 2021). "In glioma cells, ER stress induces CREB3L1 that, in turn, negatively modulates the expression of chondroitin sulfate proteoglycan and is associated with increased ability of tumor cell migration/invasion." (PMID 31064137, 2019). "Three genes, including STK11, SFRP1 and CREB3L1, were involved in tumor-associated signaling pathway, and selected for further RT-PCR analysis." (PMID 27385214, 2016). "Decreased CREB3L1 mRNA expression was associated with increased tumor grade and reduced progression-free survival." (PMID 26810754, 2016). "Moreover, DNA methylation decreases CREB3L1 mRNA expression, which is associated with increased tumor stage and shortened progression-free survival in patients with TNBC." (PMID 40149562, 2025). "Creb3l1 has been mostly found to be associated with tumor progression in the nervous system." (PMID 35186168, 2022). "Given that CREB3L1 was closely associated with ECM signaling, we investigated whether CREB3L1 was involved in shaping the tumor stromal microenvironment." (PMID 36192735, 2022). "The functions and mechanisms of CREB3L1 mutations are largely unknown in human neoplasms, and our investigation shed highlights on the potential roles of CREB3L1 mutations in cancer initiation and progression." (PMID 36171879, 2022). "Importantly, bioinformatics analyses of tumor databases support these findings, with methylation of the CREB3L1 gene associated with TNBCs, and strongly negatively correlated with CREB3L1 mRNA expression." (PMID 26810754, 2016). "Thus, the loss of CREB3L1 is a frequent occurrence and could play an important role in tumor progression and metastasis in many cancer types." (PMID 26810754, 2016). "CREB3L1 is implicated in tumor growth and metastasis through the activation of ECM signaling pathways, remodeling the tumor microenvironment." (PMID 40988561, 2026). "Our study has identified ROR1, a known oncogene, to be an upstream epigenetic regulator of a tumor suppressor, CREB3L1, in MDA-MB-231 and HCC1806 TNBC cell lines." (PMID 40427627, 2025). "CREB3L1 is a transcription factor that plays tumor-suppressive roles in TNBC and is commonly epigenetically silenced in patients." (PMID 40427627, 2025). "GTSE1+ OB cells, monocytes, CD8+ T cells, CREB3L1+ CB cells, and fibroblasts jointly coordinated the formation of pro-metastatic tumor microenvironment." (PMID 40831537, 2025). "Through RRBS we observed that CREB3L1, a known tumor suppressor in TNBC, was one of the genes that had significant differential methylation patterns when ROR1 was knocked down in MDA-MB-231 cells." (PMID 40427627, 2025). "Our findings indicate that the methylation of sites near the promoter region of the CREB3L1 tumor suppressor gene decreases when ROR1 is knocked down." (PMID 40427627, 2025).